INS (insulin)
Diseases named in the same sentence as INS in open-access papers (continued):
Sharing a sentence is not in itself a finding about the gene and the disease.
cardiovascular disease (continued). "The community group increased physical activity, reduced insulin, cardiovascular disease risk markers, increased QOL and was cost-effective." (PMID 31366999, 2019). "Another study also reported that exercise improves systemic glucose regulation and insulin sensitivity while decreasing cardiac fibrosis and oxidative stress, thereby reducing the risk factors for cardiovascular disease." (PMID 31842522, 2019). "The values that have been reported as predictors of the increased risk of clinical syndromes related to defect in insulin action and cardiovascular disease." (PMID 30158976, 2018). "Activation of PPAR-γ stimulates differentiation to insulin-sensitive smaller adipocytes and redistributes fat from visceral to subcutaneous depots, a pattern that has been associated with lower cardiovascular disease (CVD) risk." (PMID 29163673, 2017). "There were no changes over time or differences between groups in markers of peripheral insulin sensitivity, adipose tissue metabolism, or other biomarkers of cardiovascular disease risk." (PMID 28753161, 2017). "Urinary sodium concentration was associated with age, sex, history of cardiovascular disease, use of diuretics, use of insulin, eGFR, uACR, UK, U : Pcreat, estimated 24 h Na excretion, NT-proBNP, and glycosuria." (PMID 28255559, 2017). "This is a serious situation and needs to be underlined since in T1DM patients, poor metabolic control is usually due to inadequacies in insulin regimens and these patients are at highest risk for complications and cardiovascular disorders even at an early age." (PMID 27353561, 2016). "The decrease of plasma adiponectin level was associated with the increase of body mass index, decreased insulin sensitivity, and increased risk of cardiovascular disease." (PMID 27827939, 2016). "Other studies have also shown that increased PA can reduce the risk of cardiovascular disease and metabolic risk factors including insulin, already in children." (PMID 27590045, 2016). "The association of physical activity with insulin sensitivity was significant after adjustment for demographic variables, prevalent cardiovascular disease, and eGFR, but somewhat attenuated with further adjustment for fat mass." (PMID 27876008, 2016). "Intervention trials have shown that soluble dietary fiber lowers blood cholesterol concentrations, reduces blood pressure, promotes body weight loss, and improves insulin sensitivity, eventually leading to reduced risk of cardiovascular disease." (PMID 26337448, 2015). "Reverse causation introduced by a rapidly deteriorating cardiovascular disease resulting in final life-days switching on insulin was prevented by enforcing at least 6 months of “immortality” following insulin initiation." (PMID 26176017, 2015). "Altered insulin signaling in endothelial cells has emerged as an important mechanism for the increased susceptibility to cardiovascular disease." (PMID 26521236, 2015). "The implications of blood pressure, lipid profile, and insulin in school-aged children for later risk of cardiovascular disease is uncertain." (PMID 25330302, 2014). "High values of atherogenic indexes (TC/HDL-C, LDL-C/HDL-C and apoB/apoA-I) have been reported to be risk factors for cardiovascular disease that led to insulin resistant." (PMID 24558984, 2014). "DKA, cardiovascular diseases and acute exacerbation of bronchial asthma were significantly associated with the insulin regimen used." (PMID 25181406, 2014). "This study has demonstrated that daily injections of OCN produced significant effects on glucose and lipid metabolism, as well as improving insulin sensitivity, in ApoE-KO mice, all of which represent risk factors of cardiovascular disease." (PMID 24708830, 2014). "For example, exercise appears to improve BMI z-score as well as several other body composition (body weight, BMI in kg/m2, BMI percentile, fat mass, percent body fat) and cardiovascular disease risk factors (TG, fasting insulin, VO2max in ml." (PMID 25204857, 2014).
cardiovascular disease (continued). "Since adiponectin plays a role in regulating insulin function and is negatively associated with risk factors for cardiovascular disease, the clinical effects of GTE on adiponectin merits further clarification." (PMID 24614112, 2014). "In fact, height is inversely associated with cardiovascular disease and cardiovascular risk factors, such as insulin resistance." (PMID 23282078, 2013). "Regarding the associations between dietary patterns and cardiovascular disease risk factors, only a trend was observed for lower fasting insulin levels with higher scores for the Prudent dietary pattern (r = −0.32, p = 0.07)." (PMID 24330454, 2013). "CRP is a strong predictor of cardiovascular disease which improves following weight loss and reduction of insulin sensitivity." (PMID 23986778, 2013). "No meta-analysis thus far, has compared the strength of association between HOMA-IR and cardiovascular disease to associations between fasting glucose, fasting insulin and cardiovascular disease." (PMID 23300589, 2012). "In this meta-analysis, the relative risk of cardiovascular disease was higher for an increase of one standard deviation in HOMA-IR compared to an increase of one standard deviation in glucose or insulin." (PMID 23300589, 2012). "The relative risk of cardiovascular disease was higher for an increase of one standard deviation in HOMA-IR compared to an increase of one standard deviation in fasting glucose or fasting insulin concentration." (PMID 23300589, 2012). "The most frequently prescribed drugs included blood glucose lowering drugs excluding insulin (73%) and medication for cardiovascular diseases or risk management including lipid modifying agents (64%), and antithrombotic agents (37%)." (PMID 22359520, 2011). "Of greater clinical relevance is evidence that the metabolic benefit and decrease in risk of cardiovascular disease following weight loss occurs primarily in those overweight/obese individuals that are also insulin-resistant." (PMID 19936118, 2009). "Weight gain adversely affects insulin sensitivity, lipid levels and blood pressure and thereby increases the risk of cardiovascular disease." (PMID 18387078, 2008). "In other words, raised fasting insulin levels increased the women's risk of developing cardiovascular disease." (PMID 17760500, 2007). "One cannot assume that associations of glucose and insulin metabolism with cardiovascular disease will be similar in women and men." (PMID 17760500, 2007). "There is evidence that the use of feminizing hormones may have adverse effects on lipid profile and insulin sensitivity, increasing the risk of cardiovascular disease." (PMID 40648620, 2025). "However, there is some evidence that CP levels are a better predictor of cardiovascular disease and overall mortality than serum insulin levels, while also supporting the increased mortality risk associated with an insulin-resistant state." (PMID 40978759, 2025). "Furthermore, patients with PCOS often present with hormonal abnormalities, including hyperandrogenism and elevated insulin levels, which can independently contribute to vascular endothelial dysfunction and exacerbate the risk of cardiovascular disease." (PMID 40550985, 2025). "Previous studies have demonstrated that the MD improves insulin sensitivity, reduces visceral fat accumulation, and promotes a favorable lipid profile, factors that lower the risk of metabolic and cardiovascular diseases." (PMID 40289929, 2025). "Some studies have shown that insulin level increases the risk of cardiovascular disease." (PMID 38184598, 2024). "Reducing DED may reduce risk of cardiovascular disease and improve insulin sensitivity in school-aged children." (PMID 38463689, 2024).
cardiovascular disease (continued). "Consuming appropriate amounts of dietary fiber not only improves diet quality, gastrointestinal dynamics, and food digestion but also reduces the risk of cardiovascular diseases and cancer, insulin secretion, blood cholesterol levels, and the production of enterogenic virus toxins." (PMID 39479695, 2024). "Most of the 32 metabolites we discovered were novel and regulated coagulation, cytokine release, lipid oxidation, inflammation, cellular toxicity, insulin resistance, urea and malate–aspartate cycle dysregulation, and especially the risk of cardiovascular diseases." (PMID 39519188, 2024). "However, insulin actions remain a subject of debate with respect to the risk of adverse cardiovascular disease events, which can increase in individuals exposed to high insulin doses." (PMID 39092773, 2024). "These taxonomic findings are supported by multiple alterations in microbiota lipid metabolism during GAHT in our cohort, providing further insights into the implications of microbiota-lipid interactions on body composition, insulin sensitivity, inflammation, and cardiovascular disease risk." (PMID 39218875, 2024). "Reducing DED may result in a lower risk of cardiovascular disease, better insulin sensitivity, and inflammatory profile in children living in rural Mexico." (PMID 38463689, 2024). "Meta-analyses reveal that walking-based interventions are effective at improving aerobic capacity, insulin sensitivity and other cardiovascular disease risk factors such as blood pressure and waist circumference, but often fail to significantly improve serum lipid profiles." (PMID 39570874, 2024). "Loss of insulin sensitivity and metabolic flexibility can result in cardiovascular disease." (PMID 38796064, 2024). "Changes in miRNA expression following surgery could potentially reflect, influence, or predict the metabolic improvements observed in patients, such as weight loss, improved insulin sensitivity, and reduced risk of cardiovascular diseases." (PMID 38916799, 2024). "Overall, based on similar previous studies, interval's superiority in boosting vascular function and preventing endothelial injuries over Cont is owing to its more substantial impact on cardiovascular disease risk factors, insulin resistance, oxidative stress, and inflammation." (PMID 39742025, 2024). "Blood level of selenium was positively associated with TyG and TyG-BMI, indicating that excessive blood selenium may be associated with impaired insulin sensitivity and increased risk of cardiovascular disease." (PMID 37145256, 2024). "Moreover, the dietary insulin index (DII) and dietary insulin load (DIL) have been shown to potentially elicit favorable effects on cardiovascular disease (CVD) risk." (PMID 38268038, 2024). "Similarly, the relationships between TyG-BMI, TG/HDL-C, and METS-IR with ESCC risk were influenced by sex, age, smoking, insulin levels, and cardiovascular disease (P for interaction < 0.05)." (PMID 39180548, 2024). "In addition to lessening the effects of cardiovascular disease risk factors, “previous studies reported positive effects of a [paleo diet] on energy intake, body composition, [and] insulin sensitivity”." (PMID 36771398, 2023). "The progression of MetS to overt cardiovascular disease is multifactorial and complex and may be linked to visceral fat, insulin resistance, inflammatory responses, and sympathetic activation." (PMID 37060185, 2023). "Given the high risk for T1D patients to develop cardiovascular diseases, and the established role of impaired insulin and autophagy pathways in these diseases, we proposed to analyze the impact of an ACE inhibitor, Cap on the metabolic impairments in a T1D mouse model." (PMID 38092813, 2023). "Although increased circulating GDF-15 levels have been closely associated with cardiometabolic disorder and cardiovascular disease, its elevation may also reflect insulin responsiveness and the therapeutic effects of antidiabetic medications." (PMID 35883490, 2022).
cardiovascular disease (continued). "Novel contributing mechanisms are also emerging, such as the indirect effects of CAs on insulin sensitivity through adiponectin.DM is known to be a risk factor for cardiovascular diseases, which may explain the more patients in PPGL-CCs group suffered from DM." (PMID 35721724, 2022). "It has been reported that treatment with canagliflozin improves adipose tissue functions; modifies levels of serum leptin, adiponectin, and interleukin 6; and may favorably affect insulin sensitivity and other risk factors for cardiovascular disease." (PMID 35884961, 2022). "Excessive consumption of milk fat concentrations of C12:0, C14:0, and C16:0 fatty acids in human diets is a recognized risk factor for cardiovascular disease and can lower insulin sensitivity, while C18:0 is considered as having neutral effects on circulating plasma cholesterol concentrations." (PMID 35326136, 2022). "Those insulin-resistant, dyslipidemic patients are at increased risk of cardiovascular disease." (PMID 34007274, 2021). "Moreover, our data suggests insulin directly affects metabolomic measures previously associated with increased cardiovascular disease risk." (PMID 34106350, 2021). "Muscle fitness was measured by handgrip strength and standing long jump, whereas the cardiovascular disease risk score was composed of the z-scores of two skinfolds, systolic blood pressure, insulin, glucose, triglycerides, and total cholesterol/high density lipoprotein cholesterol." (PMID 34828759, 2021). "Human studies have shown that high‐intensity interval training (HIIT) is more effective than MICT in improving arterial vascular function and can positively affect cardiopulmonary health, traditional cardiovascular disease risk factors, oxidative stress, inflammation and insulin sensitivity." (PMID 34331512, 2021). "Insulin signaling and resistance are implicated in the pathogenesis of cardiovascular disease." (PMID 35069436, 2021). "Several lines of evidence reveal that tennis can improve cardiopulmonary function, reduce the risk for cardiovascular disease and stress, and develop a strong heart and better fitness levels, lower insulin concentration during exercise, and enhance the capacity to cope with stress." (PMID 33573269, 2021). "Additionally, a case-control study of 836 T2DM patients reported higher cardiovascular disease risk in subjects with high-dose insulin therapy." (PMID 33598483, 2021). "These functional variants are associated with altered risk of cardiovascular disease and insulin sensitivity, and may contribute to heterogeneity in response to sEHI therapy between individuals." (PMID 32545637, 2020). "Moreover, poor zinc status has been linked with decreased insulin secretion and insulin insensitivity and low blood selenium concentrations with an increased incidence of cardiovascular disease (CVD)." (PMID 33365325, 2020). "This study aimed to investigate the linkage between adipocytokines and insulin with the cardiovascular disease risk, with particular reference to the adipokines galectin-3, plasminogen activator inhibitor-1, and interleukin-1-beta, C-reactive protein, and monocyte chemoattractant protein." (PMID 32290863, 2020). "In a recent meta-analysis of 65 studies involving 516,325 participants, the relative risk of cardiovascular disease was higher for an increase of one standard deviation in HOMA-IR compared to an increase of one standard deviation in fasting glucose or fasting insulin concentration." (PMID 33234146, 2020). "We found changes in copper were negatively associated with changes in fasting apoCIII, a lipoprotein implicated as a cardiovascular disease risk factor, and ceruloplasmin ferroxidase activity was negatively associated with increases in post-meal glucose, insulin, and lactate responses." (PMID 32854403, 2020).
cardiovascular disease (continued). "Impaired insulin and glucose levels are implicated in the etiology of cardiovascular disease; however, their influence on the formation and composition of atherosclerotic plaque remains unclear." (PMID 31958313, 2020). "Indeed, SIRT1 is differently regulated in many oxidative-stress-associated diseases i.e., neurodegenerative and cardiovascular disease and increases insulin sensitivity in T2D and aging." (PMID 31614723, 2019). "In addition to preferential glucose oxidation in VincHE flies, metabolic studies also revealed decreased abundance of metabolites associated with aging, insulin sensitivity, and cardiovascular disease." (PMID 30105314, 2018). "Ideally, reducing sympathetic tone by RDN could improve both blood pressure and insulin sensitivity, thus targeting two important risk factors of cardiovascular disease." (PMID 29082259, 2017). "Due to its trafficking function, the GOSR2 gene could be associated with the cardiovascular diseases which are highly associated with macromolecules such as insulin, leptin, and angiotensinogen." (PMID 29137253, 2017). "Other factors selected using the full sample, such as current smoking, insulin use, and educational attainment with all-cause mortality and history of cardiovascular disease with CVD mortality, were also included in the models selected using a two-fold cross-validation approach." (PMID 26146522, 2015). "Indeed, the cellular mechanisms underlying the insulin resistant state have been suggested to explain the observed relationship between low lung function with either cardiovascular disease or all-cause mortality in many epidemiologic studies." (PMID 26542243, 2015). "Moderate alcohol consumption has been previously reported to improve insulin sensitivity, and consequently may further contribute to the lower risk of cardiovascular disease." (PMID 26488726, 2015). "Conversely, cardiovascular disease was also significantly associated with the insulin regimen used (p = 0.005), but the number of cardiovascular disease cases in which basal-bolus insulin was used was approximately double that of sliding-scale insulin." (PMID 25181406, 2014). "In addition, we found that DKA, cardiovascular diseases and acute exacerbation of bronchial asthma appeared to have a significant association with the insulin regimens used in glycemic control." (PMID 25181406, 2014). "In one case control study of 150 overweight children with biopsy proven NAFLD versus those without, NAFLD was found to be strongly associated with risk factors for cardiovascular disease, including higher glucose, insulin, blood pressure, TC, LDL, triglyceride, and lower HDL." (PMID 25126490, 2014). "A reduction in adiposity may be associated with an improvement in insulin sensitivity and β-cell function as well as cardiovascular disease (CVD) risk factors; however, few studies have investigated these associations in a longitudinal setting." (PMID 23483954, 2013). "Studies suggest that chromium deficiency may increase the risk of cardiovascular diseases, elevate the blood glucose, lipid, and insulin level, and decrease the BMI." (PMID 24639797, 2013). "We hypothesized that HOMA-IR is more strongly associated with incident cardiovascular disease than fasting glucose or fasting insulin." (PMID 23300589, 2012). "In addition to dietary modifications, the inclusion of more physical activity is often indicated to stimulate weight loss, increase energy expenditure and promote improvements in insulin sensitivity as well as other indicators of cardiovascular disease risk." (PMID 21092228, 2010). "In this respect, circulating GLP-1 may be a novel biomarker for improving insulin sensitivity in high -risk patients for cardiovascular disease." (PMID 20470376, 2010). "Similarly, in a recent meta-analysis of the association of insulin with cardiovascular disease just 11% of the cases were female and the mean age of participants was less than 60 y in all of the included studies." (PMID 17760500, 2007).